AOC4P (amine oxidase copper containing 4, pseudogene)
Synonyms: UPAT
Gene: Transcribed unprocessed pseudogene on chromosome 17 (42,867,279 to 42,874,369, forward strand). Ensembl gene ENSG00000260105.
Diseases named in the same sentence as AOC4P in open-access papers:
AOC4P is named in the same sentence as 10 diseases in open-access papers, as found by Europe PMC text mining. Sharing a sentence is not in itself a finding about the gene and the disease. The quoted sentences say what the papers report.
gastric cancer (9 papers, 2019 to 2025). A primary or metastatic malignant neoplasm involving the stomach. "Knockdown of AOC4P inhibits gastric cancer cell proliferation, migration, invasion, and promotes apoptosis in vitro, while reducing tumor growth in vivo." (PMID 40556338, 2025). "The research discovered significant increase of plasma lncRNA (TINCR, CCAT2, AOC4P, BANCR, and LINC00857) in gastric cancer cell lines." (PMID 33473276, 2021). "Similarly, lncRNAs, such as H19, TINCR, AOC4P, BANCR, LINC00857, and CCAT2, are detectable in body fluids and can be used to efficiently differentiate gastric cancer patients from healthy controls." (PMID 34885213, 2021). "Evidence has also shown the involvement of AOC4P in colorectal cancer (CRC) and gastric cancer (GC)." (PMID 32334623, 2020).
hepatocellular carcinoma (2 papers, 2020 to 2021). A malignant tumor that arises from hepatocytes. "AOC4P is a lncRNA involved in hepatocellular carcinoma and colorectal cancer and ADHFE1 is a breast cancer oncogene." (PMID 33892787, 2021). "The copper containing 4, pseudogene (AOC4P) is a recently discovered EMT-related lncRNA that was initially reported in hepatocellular carcinoma (HCC)." (PMID 32334623, 2020).
gastric tumors (1 paper, 2025). "AOC4P is overexpressed in gastric tumors and linked to poor survival and lymphovascular invasion." (PMID 40556338, 2025).
tumor (7 papers, 2015 to 2025). "The reduced expression of AOC4P is closely associated with advanced tumor stage and distant metastasis." (PMID 40556338, 2025). "Then, a tumour EMT RT-PCR array indicated that certain differentially expressed genes were identified after the knockdown of AOC4P expression." (PMID 32334623, 2020). "In line with the results of the in vitro assays, an in vivo experiment indicated that silencing AOC4P led to a remarkable increase in the number, weight and distribution of the tumour." (PMID 32334623, 2020). "After validation in 108 HCC specimens, we identified a differentially expressed novel tumor suppressive lncRNA termed amine oxidase, copper containing 4, pseudogene (AOC4P)." (PMID 26160837, 2015). "In this study, we identified a novel tumor suppressor lncRNA, termed amine oxidase, copper containing 4, pseudogene (AOC4P), via microarray analysis and subsequent validation in HCC tissue specimens." (PMID 26160837, 2015). "In conclusion, our data show that the lncRNA AOC4P exerts a tumor-suppressive effect on HCC tumor progression." (PMID 26160837, 2015). "In this study, we identified a novel lncRNA, AOC4P, and demonstrated its tumor-suppressive effect on HCC." (PMID 26160837, 2015). "Taken together, our findings suggest that AOC4P lncRNA acts as an HCC tumor suppressor by enhancing vimentin degradation and suppressing the EMT." (PMID 26160837, 2015). "To further validate the tumor-suppressive function of AOC4P, we performed an in vivo xenograft assay and a tail vein migration assay using nude mice." (PMID 26160837, 2015). "Evidence also supported that AOC4P regulated tumor cell proliferation and invasion in GC." (PMID 32334623, 2020). "We have also shown that low expression levels of AOC4P are positively related with an advanced tumour stage and lymph node metastasis in EOC, suggesting that AOC4P could serve as an effective target for anti-metastatic strategies in EOC." (PMID 32334623, 2020). "The downregulation of AOC4P in HCC suggested its potential function as a tumor suppressor." (PMID 26160837, 2015). "Furthermore, a correlation analysis of AOC4P expression with clinicopathological parameters revealed that the AOC4P expression level was predominantly decreased in late-stage tumor tissues (Kruskal-Wallis test p = 0.0207) and negatively correlated with tumor size (Wilcoxon rank-sum test p = 0.0551)." (PMID 26160837, 2015). "Microarray analyses revealed several differentially expressed lncRNAs; among them, five novel lncRNAs, TINCR, CCAT2, AOC4P, BANCR, and LINC00857, were detected in tumor tissue samples and pre and post-operative plasma." (PMID 37670949, 2023). "In this study, we found that AOC4P downregulated vimentin expression, thereby reducing HCC tumor growth and metastasis." (PMID 26160837, 2015).
malignant tumors (1 paper, 2021). "Several lncRNAs identified in other malignant tumors, such as HOTAIR, CCDC26, and AOC4P, have also been evaluated in GISTs and were shown to be associated with GIST metastasis and sensitivity to imatinib." (PMID 34218261, 2021).
AOC4P also shares sentences with these, for which no sentence is quoted: breast carcinoma (1 paper); colorectal cancer (1); liver cancer (1); lymph node metastasis (1); spontaneous abortion (1).